APLNR (apelin receptor)
Diseases named in the same sentence as APLNR in open-access papers (continued):
Sharing a sentence is not in itself a finding about the gene and the disease.
renal fibrosis (6 papers, 2021 to 2024). A final common manifestation of a wide variety of chronic kidney diseases characterized by glomerulosclerosis and tubulointerstitial fibrosis. "APLNR has been shown to be involved in renal fibrosis by acting on TGF-β1 and its expression was associated with chronicity index (CI) of LN." (PMID 34604256, 2021). "Hsa_circ_0123190 can regulate APLNR expression involved in renal fibrosis by sponging hsa-miR-483-3p in LN." (PMID 33436040, 2021). "Numerous evidences indicate that apelin and APLNR play a key role in various kidney diseases, such as renal fibrosis, renal ischemia/reperfusion injury, polycystic kidney disease, and diabetic nephropathy." (PMID 33436040, 2021). "Spongeing hsa-miR-483-3p, interacted with APLNR, and participated in renal fibrosis of LN." (PMID 39835138, 2024). "And then, we further explored that hsa_circ_0123190 was a novel biomarker of peripheral blood for LN and could act as a sponge for hsa-miR-483-3p to regulate APLNR expression involved in renal fibrosis in LN." (PMID 33436040, 2021). "APLNR, as apelin receptor, was involved in renal fibrosis by regulating the expression of TGF-β1." (PMID 33436040, 2021). "Therefore, hsa_circ_0123190 might contribute to renal fibrosis in LN by modulating the hsa-miR-483-3p/APLNR/TGF-β1 axis." (PMID 34604256, 2021). "Therefore, we tentatively hypothesized APLNR may be involved in renal fibrosis of LN by regulating TGF-β1." (PMID 33436040, 2021). "This interaction affects the expression of the apelin receptor (APLNR) gene, which is related to renal fibrosis, highlighting the critical role of hsa_circ_0123190 in inhibiting LN pathogenesis." (PMID 39239069, 2024).
breast carcinoma (5 papers, 2019 to 2025). "To assess whether Apelin exerts its effects in the tumor epithelial cells or in the tumor endothelial cells, we used the E0771 mammary cancer model and specifically downregulated the expression of the Apelin receptor (Aplnr) in the cancer cells using shRNA (Fig EV2B)." (PMID 31267692, 2019).
gastric cancer (5 papers, 2018 to 2025). A primary or metastatic malignant neoplasm involving the stomach. "Moreover, this study found several prognostic markers worth exploring: APLNR is a risk factor for GC, so blocking the Apelin/APLNR axis to inhibit the development of gastric cancer is a promising new therapy." (PMID 35174205, 2022). "Moreover, inhibition of APLNR by siRNA reduced the proliferation rate, migration, and invasion abilities of GC cells, suggesting a role for the apelinergic system in the progression of gastric cancer." (PMID 29875677, 2018).
liver fibrosis (5 papers, 2017 to 2025). "Apelin and APLNR can also be expressed in hepatic stellate cells and macrophages, affecting liver fibrosis in MASLD." (PMID 39744169, 2025). "Treatment with the F13A, an apelin receptor antagonist, alleviated hepatic fibrosis and vessel density and improved cardiovascular performance in rats with cirrhosis." (PMID 29340118, 2017).
lung adenocarcinoma (5 papers, 2018 to 2025). A carcinoma that arises from the lung and is characterized by the presence of malignant glandular epithelial cells. "Immunohistochemical analysis for detecting the apelin receptor, APJ, showed that tumors from patients with lung adenocarcinoma had high levels of APJ compared to adjacent tissue." (PMID 36291097, 2022).
Anxiety (4 papers, 2017 to 2021). Intense feelings of nervousness, tension, or panic often arise in response to interpersonal stresses. "The TT genotype and T allele of the APLNR rs2282623 polymorphism were associated with a higher risk of anxiety in patients with CHD (19.64% vs. 11.32% and 47.32% vs. 30.42%; P = 0.003 and P = 0.001, respectively)." (PMID 32849850, 2020). "The APLNR rs2282623 T allele was associated with an increased risk of anxiety in CHD patients after adjusting for related disease complications, with the Bonferroni correction (P-adjust = 0.022)." (PMID 32849850, 2020).
brain tumor (4 papers, 2019 to 2022). "We have gained important insight into APLN/APLNR-mediated effects in brain tumor associated neurons, astrocytes, the vasculature (consisting of ECs and pericytes), as well as the immune compartment (formed by tumor-associated myeloid cells and T-lymphocytes)." (PMID 34359800, 2021). "Here we summarize the current evidence on the role of APLN/APLNR signaling during brain tumor pathology." (PMID 34359800, 2021). "However, the relationship between APLN/APLNR and prognosis of brain tumor is still unknown." (PMID 36193059, 2022). "The GlioVis data portal of brain tumor expression datasets was used to examine the relationship between APELA and APLNR gene expression and patient survival." (PMID 30917521, 2019).
diabetic kidney disease (4 papers, 2018 to 2023). Progressive kidney disorder caused by vascular damage to the glomerular capillaries, in patients with diabetes mellitus. "ELABELA (ELA), an endogenous ligand of the apelin receptor (also known as apelin peptide jejunum [APJ]), has been shown to decrease in the plasma of patients with diabetic kidney disease (DKD)." (PMID 38018421, 2023).
glioma (4 papers, 2019 to 2024). A benign or malignant brain and spinal cord tumor that arises from glial cells (astrocytes, oligodendrocytes, ependymal cells). "In contrast, neither the APELA receptor (APLNR) nor the other ligand that binds to this receptor Apelin (APLN) was associated with patient outcome in glioma or GBM." (PMID 30917521, 2019).
Cerebral ischemia (3 papers, 2015 to 2022). Restriction of arterial blood supply to the brain associated with insufficient oxygenation to support the metabolic requirements of the tissue. "Studies increasingly show that the apelin/apelin receptor (APJ) signaling pathway is involved in the occurrence and development of cerebral ischemia." (PMID 36034795, 2022).
cholangiocarcinoma (3 papers, 2019 to 2025). A carcinoma that arises from the intrahepatic biliary tree (intrahepatic cholangiocarcinoma) or from the junction, or adjacent to the junction, of the right and left hepatic ducts (hilar cholangiocarcinoma). "In patients with cholangiocarcinoma, APLN and APLNR genes were obviously upregulated in tumor tissues compare to nonmalignant liver tissues." (PMID 36193059, 2022).
Hyponatremia (3 papers, 2021). An abnormally decreased sodium concentration in the blood. "administered LIT01-196 blocks the antidiuretic effect of vasopressin and the vasopressin-induced increase in urinary osmolality, and induces a progressive improvement in hyponatremia, suggesting that apelin receptor activation constitutes an original approach for hyponatremia treatment." (PMID 34880830, 2021). "We therefore hypothesized that activating the apelin receptor (apelin-R) with LIT01-196, a metabolically stable apelin-17 analog, may be beneficial for treating the Syndrome of Inappropriate Antidiuresis, in which AVP hypersecretion leads to hyponatremia." (PMID 33436646, 2021).
lupus nephritis (3 papers, 2021 to 2024). Glomerulonephritis in the context of systemic lupus erythematosus. "Hsa-circ-0123190 level decreased in lupus nephritis and acts by sponging hsa-miR-483-3p, which was validated to interact with the apelin receptor (APLNR)." (PMID 38967046, 2024).
neuropathy (3 papers, 2020 to 2024). A disorder affecting the nervous system that manifests with pain, tingling, numbness, and/or muscle weakness. "The APLN/APLNR pathway may also serve as a promising therapeutic target for the treatment of psychosis and neuropathy." (PMID 32849850, 2020).
prostate carcinoma (3 papers, 2019 to 2025). A carcinoma that arises from epithelial cells of the prostate gland. "In prostate cancer, high expression of Apelin Receptor (APLNR) activates the PI3K/AKT/mTOR signaling pathway, increasing levels of p-PI3K, p-AKT, and p-mTOR." (PMID 40725100, 2025).
atrial fibrillation (2 papers, 2023). A disorder characterized by an electrocardiographic finding of a supraventricular arrhythmia characterized by the replacement of consistent P waves by rapid oscillations or fibrillatory waves that vary in size, shape and timing and are accompanied by an irregular ventricular response. "In patients with atrial fibrillation and thrombosis, expression of apelin and the apelin receptor was reduced and expression of AT1 receptors and PAI-1 was increased in the left atrial appendage compared to those in sinus rhythm or atrial fibrillation without thrombosis." (PMID 37956047, 2023).
endometriosis (2 papers, 2022 to 2023). The growth of functional endometrial tissue in anatomic sites outside the uterine body. "Recently, apelin receptor APLNR was identified as one of three key genes in endometriosis." (PMID 38075048, 2023). "Notably, a recent bioinformatical analysis of microarray expression data identified the apelin receptor APLNR as one of three key genes in endometriosis." (PMID 36289764, 2022). "Although, to date, there are no further studies to elucidate the role of the apelin receptor in endometriosis, studies addressing this fact can be expected." (PMID 36289764, 2022).
genitourinary cancers (2 papers, 2021 to 2026). "The STAT3 signaling pathway and the apelin axis (apelin receptor, APLNR- and ligands, -apelin and/or -elabela), participate in the processes of kidney inflammation and fibrosis and both may be involved in muscle wasting during CKD." (PMID 42016932, 2026).
mental disorder (2 papers, 2018 to 2020). A disease that has its basis in the disruption of mental process. "We reported for the first time that the APLN rs2235310 and APLNR rs2282623 polymorphisms are associated with the risks of psychiatric disorders in CHD patients and may serve as novel biomarkers for therapy." (PMID 32849850, 2020).
Myocardial fibrosis (2 papers, 2023). "Recent data have shown that miR-185-5p targets the apelin receptor, induces collagen production and promotes myocardial fibrosis." (PMID 36983815, 2023).
nasopharyngeal carcinoma (2 papers, 2021). A carcinoma arising from the nasopharyngeal epithelium. "In nasopharyngeal carcinoma, low apelin receptor (APLNR) expression is correlated with a poor prognosis, and knockdown of APLNR can improve cell motility." (PMID 34572451, 2021).
osteosarcoma (2 papers, 2022 to 2025). A usually aggressive malignant bone-forming mesenchymal neoplasm, predominantly affecting adolescents and young adults. "In osteosarcoma, elevated APLNR expression promotes proliferation and invasion." (PMID 35140786, 2022).
ovarian clear cell cancer (2 papers, 2021 to 2025). An invasive malignant neoplasm that arises from the ovary and is characterized by a predominance of clear and hobnail malignant epithelial cells. "The dysregulation of APLNR in ovarian clear cell carcinoma (OCCC) cells was associated with growth, migration, and cell cycle progression." (PMID 40165344, 2025).
renal cell carcinoma (2 papers, 2019 to 2025). "The aim of this study is to investigate the expression of APLN (apelin) and APLNR in patients with renal cell carcinoma (RCC), and its association with clinicopathological parameters and survival." (PMID 30783205, 2019). "In our study, we provide a comprehensive characterisation of APLNR and APLN expression in renal cell carcinoma." (PMID 30783205, 2019).
renal failure (2 papers, 2020 to 2021). "Since the local RAS is obviously overactivated in patients with renal failure, it seems that the induction of the APLN/APLNR axis may influence the AngII-mediated pathophysiological effects." (PMID 33255902, 2020).
sarcopenia (2 papers, 2021 to 2023). Progressive decline in muscle mass due to aging which results in decreased functional capacity of muscles. "Among the several therapeutic interventions for CKD‐induced sarcopenia proposed over the last few decades, the apelin–apelin receptor (Apj) system has attracted some attention in recent years." (PMID 36562292, 2023). "From the GEO profiles, the sarcopenia gene set variation analysis score was correlated significantly with the mRNA expression of APLNR (p < 0.001) and HSPA2 (p < 0.001)." (PMID 33743591, 2021).
Tinnitus (2 papers, 2019 to 2023). Tinnitus is an auditory perception that can be described as the experience of sound, in the ear or in the head, in the absence of external acoustic stimulation. "The genes that were down-regulated in the tinnitus group, were influenced by more than just an outlier value, and had corresponding FC values of >1 included GFAP (logFC= −3.04), APLNR (−2.95), PREX2 (−1.44), and PLVAP (−1.04; all p < 0.01)." (PMID 37048724, 2023). "The apelin receptor APLNR was also found to be down-regulated in VS versus control nerves, although tinnitus, hearing loss, and tumor size were not separately examined." (PMID 37048724, 2023).
cardiopulmonary diseases (1 paper, 2018). "Apelin and elabela/toddler are endogenous ligands for the apelin receptor APJ, which has been shown to play a beneficial role in normal physiology and its dysregulation is associated with several cardiopulmonary diseases, including PAH." (PMID 30619886, 2018).
clear-cell renal cell carcinoma (1 paper, 2022). "The elevated serum APLNR was correlated with inferior OS in patients with clear-cell renal cell carcinoma." (PMID 36193059, 2022).
cognitive disorder (1 paper, 2023). A disease affects cognitive processes. "While the expression of both Apelin and APLNR decreases with increasing age, agonism of apelin receptors produces beneficial effects in fibrotic, cardiovascular, and cognitive disorders." (PMID 37315204, 2023).
demyelinating disease (1 paper, 2026). A broad group of disorders that affect the myelin sheaths that cover the neurons. "However, as the findings are based on descriptive analyses, further functional studies are required to determine the mechanistic contribution of APLNR signaling and its potential as a therapeutic target in demyelinating diseases." (PMID 42196494, 2026).
demyelination (1 paper, 2024). "This statement is further strengthened by our data, where the expression of APLNR decreased significantly in the remyelination group compared to the demyelination group, yet remained higher than in the control groups." (PMID 39684720, 2024).
hemangioma (1 paper, 2022). A benign vascular lesion characterized by the formation of capillary-sized or cavernous vascular channels. "Finally, three genes (APLN, APLNR, TMEM132A) were identified as hub genes, which were consistently highly expressed in hemangioma tissues, regardless of different stages, through integrated WGCNA and PPI network analysis of DEGs." (PMID 35501731, 2022).
insulinoma (1 paper, 2024). "The apelin receptor (APJ) is expressed in human islets and a rat insulinoma cell line, suggesting that apelin plays a paracrine or autocrine role in the function of pancreatic islets." (PMID 38178017, 2024).
left ventricular hypertrophy (1 paper, 2025). Enlargement of the LEFT VENTRICLE of the heart. "Cav-1 is reported to be downregulated in left ventricular hypertrophy (LVH) rat models and hypertrophic cardiomyocytes induced by apelin-13/apelin receptor (APJ), and autophagy pathway is also activated in vitro." (PMID 41030451, 2025).
liver cirrhosis (1 paper, 2021). "There is an emerging consensus that apelin receptor density is upregulated in liver cirrhosis." (PMID 33171278, 2021).
nutritional disorder (1 paper, 2013). Any condition related to a disturbance between proper intake and utilization of nourishment. "Microarray results obtained in juvenile hearts, which showed higher expression of apelin receptor in OF mice, encouraged us to explore some of the components of this adipocytokine system more thoroughly, given its increasing pathophysiological significance in nutritional disorders." (PMID 23468899, 2013).
pancreatic cancer (1 paper, 2022). "Our data clearly establish that the co-expression of apelin and APJ by pancreatic tumor cells fosters tumor growth, whereas loss of the apelin receptor dramatically reduces the tumor burden in murine orthotopic xenograft experiments." (PMID 36142542, 2022). "Apelin receptor blockades reduced cancer cell proliferation along with a reduction in pancreatic tumor burden." (PMID 36142542, 2022). "Of interest, the inhibition of the apelin receptor by shRNA expression in pancreatic tumor cells significantly slows down cancer cell proliferation." (PMID 36142542, 2022).
Parkinson disease (1 paper, 2023). A progressive degenerative disorder of the central nervous system characterized by loss of dopamine producing neurons in the substantia nigra and the presence of Lewy bodies in the substantia nigra and locus coeruleus. "The low expression of APLNR was associated with ECM receptor interaction, whereas the high expression of APLNR was associated with Parkinson’s disease." (PMID 37492566, 2023).
pulmonary atresia (1 paper, 2020). "We conducted this study involving children with pulmonary valvular stenosis (PS) or pulmonary atresia with intact ventricular septum (PA/IVS) to evaluate the potential of a new endogenous ligand of apelin receptor, Elabela (ELA), as a potential biomarker for right heart overload." (PMID 33282918, 2020).
Right ventricular hypertrophy (1 paper, 2024). In this case the right ventricle is more muscular than normal, causing a characteristic boot-shaped (coeur-en-sabot) appearance as seen on anterior- posterior chest x-rays. "Targeting the apelin receptor with the novel, G protein-biased peptide agonist, MM07, is hypothesised to reverse the developed symptoms of elevated right ventricular systolic pressure and right ventricular hypertrophy." (PMID 38655187, 2024).
septic shock (1 paper, 2024). Shock caused by infection; frequently caused by gram negative bacteria, although some cases have been caused by other bacteria, viruses, fungi, and protozoa; characterized by fever, chills, tachycardia, tachypnea, and hypotension. "Also, the inclusion of other apelin receptor -APJ- agonists (i.e., APL-17, APL-36, Ela) would have helped in identifying the best agonist, amongst the currently studied ones, when it comes to cardiovascular improvements and NE-sparing in the context of septic shock." (PMID 39103658, 2024).